EGFR (epidermal growth factor receptor)
Diseases named in the same sentence as EGFR in open-access papers (continued):
Sharing a sentence is not in itself a finding about the gene and the disease.
glioma (continued). "The astrocytes probably suffer such transition during tumorigenesis to the EGFR-amplified glioma cells." (PMID 35521558, 2022). "Gαi1 can form a complex with multiple RTKs (including FGFR, PDGFR and EGFR), transducing downstream Akt-mTOR activation in glioma tissues and cells." (PMID 35280670, 2022). "Meanwhile, gene upregulation is often accompanied by gene amplification in gliomas; for example, EGFR expression is strongly affected by EGFR amplification." (PMID 34697421, 2022). "Further transformation of low-grade gliomas with an IDH mutation to secondary GBM requires more genetic alterations, such as the amplification of epidermal growth factor receptor (EGFR) and lost expression of the phosphatase and tensin homolog (PTEN)." (PMID 35626018, 2022). "Like EGFR, PDGFRA was reported to be highly expressed, amplified, mutated, or truncated in gliomas 37-40." (PMID 35002529, 2022). "Hopefully, some novel therapies emerged in recent years, like chimeric antigen receptor-T cell (CAR-T) therapy targeted on EGFR vIII and nanoparticle delivery of EGFR inhibitors, but their real effectiveness in gliomas is yet to be explored." (PMID 36338770, 2022). "Fluorescence-guided surgical imaging using panitumumab, an EGFR antibody, conjugated to IRDye800 was used to detect gliomas in real time, demonstrating good tumor-to-background contrast ratio." (PMID 35701793, 2022). "On downstream of the signaling pathway, the authors demonstrated that Tau blocked the mesenchymalization of EGFR glioma cells by inhibiting NF-κB phosphorylation and by reducing the amount of TAZ protein." (PMID 36358803, 2022). "In particular, in this third molecular type fall pleomorphic-xantoastrocytoma (PXA)-like pHGGs, v-myc myelocytomatosis viral-related oncogene (NMYC), platelet-derived growth factor receptor A (PDGFRA), or EGFR amplified gliomas and hypermutant pHGGs." (PMID 35456430, 2022). "Considering that H3.3K27me3 loss is the main molecular feature of both the H3.3K27M mutant and diffuse midline EGFR mutant gliomas, it has been proposed that these tumors be grouped under the denomination of H3.3K27-altered pHGGs." (PMID 35456430, 2022). "Our previous research established that IGFBP2 potentiates STAT3 transactivation activities by increasing nuclear EGFR amounts in glioma." (PMID 36556226, 2022). "GSC gliomas showed significant heterogeneity and invasiveness on imaging, and exhibited strong expression of Ki-67, partial expression of EGFR and VEGF, and weak expression of MGMT and HIF-1α on immunohistochemical staining." (PMID 36591483, 2022). "Then and more interestingly, they found that Tau protein inhibits angiogenesis and favors vascular normalization in gliomas expressing wild-type EGFR." (PMID 36358803, 2022). "SHC proteins are involving in the epidermal growth factor receptor (EGFR) internalization process and the increased expression level of SHC4 in glioma promoted the phosphorylation of EGFR specific sites." (PMID 35033067, 2022). "In gliomas, EGFR amplification promotes invasion, proliferation, and failure of radiotherapy and chemotherapy." (PMID 35888045, 2022). "We used a glioma model in Drosophila melanogaster that results from the overexpression of constitutively active forms of EGFR and PI3K specifically in glial cells." (PMID 35455961, 2022). "Exosomal miR‐146b decreases EGFR and NF‐κB protein in glioma cells and therefore reduced glioma growth in vitro." (PMID 35587712, 2022). "Previous research revealed that THZ1 treatment induces EGFR and PDGFRa expression and multiple downstream oncogenic signalling pathways in glioma." (PMID 36076237, 2022).
glioma (continued). "The ROC analysis showed that R2’ was able to differentiate EGFR amplification status in treatment-naïve IDH wild-type gliomas with a threshold of 5.71 s−1 (AUC 0.71, sensitivity 66.7%, specificity 76.9%, accuracy 73.7%)." (PMID 35626127, 2022). "Recent findings support an oncogenic role of CRNDE in glioma, whereby its upregulation is positively correlated with activation of EGFR signaling." (PMID 35999564, 2022). "At present, small-molecule inhibitors of EGFR have been proven to increase the sensitivity of temozolomide-resistant glioma." (PMID 35903366, 2022). "The study showed miR146b decreased motility and invasion of glioma cells, and its target being Epidermal Growth Factor Receptor (EGFR) mRNA." (PMID 36536420, 2022). "We demonstrated a proof of concept for the presence of autoantibodies against the EGFR phospho-peptide S1166 in plasma of high-grade glioma patients." (PMID 35563452, 2022). "Inhibitor of differentiation 3 (ID3)-induced increases in IL-6 and IL-8 are significantly decreased by treatment with an EGFR inhibitor that directly dephosphorylates AKT in glioma cells." (PMID 36341365, 2022). "Subsequent studies in glioma revealed both the pro-tumorigenic potential of Lyn, featuring its mediation of augmented stress resistance of gliomas, invasive potential, EGFR downstream mediator to promote cellular migration, as well as a tumor-suppressive role." (PMID 35628503, 2022). "TRIM24 overexpression is characteristic of gliomas and is required for EGFR activation and for STAT3 recruitment and stabilization, which is important for exerting its oncogenic potential." (PMID 36139694, 2022). "In this study, the role of MUC4, MMP9, and EGFR in the progression and clinical outcome of glioma patients was investigated." (PMID 36400876, 2022). "To further validate the results, we checked the levels of key proteins in the EGFR pathway from two Glioma cell lines through western blotting." (PMID 35436989, 2022). "Existing study suggested that MCM8 was regulated by EGFR signaling and interacted with DNA-replication-initiating factors to promote the growth of glioma stem cells." (PMID 36575045, 2022). "MicroRNA-34a (micR-34a) is also relate to the PD-L1 expression in gliomas, which modulates EGFR or PD-L1 translation for suppressing tumors." (PMID 36741734, 2022). "Latest reports have shown that these miRNAs by regulation PDCD4, WNT5A, MET, and EGFR also serves certain biological function in the progression of various human tumors including glioma." (PMID 35646622, 2022). "GALNT2G knockdown or overexpression promotes or inhibits O‐glycosylation and phosphorylation of the epidermal growth factor receptor, respectively, to affect the malignant properties of gliomas." (PMID 37786890, 2022). "The linkage of boron containing liposomes to monoclonal antibodies such as Cetuximab has allowed for in-vitro targeting of epidermal growth factor receptor (EGFR) expressing rat glioma cells." (PMID 35740674, 2022). "Regarding the mechanism, we clarify that EGFR signaling was regulated by GBP2, and also demonstrated that GBP2 directly interacted with KIF22 and regulated glioma progression through KIF22/EGFR signaling." (PMID 35436989, 2022). "This variant is constitutively activated owing to the loss of the ligand-binding domain and has different roles compared with EGFR amplification in gliomas." (PMID 36338770, 2022). "In previous studies, we demonstrated that iPA interferes with EGFR signaling reducing glioma cell viability." (PMID 35393392, 2022). "Since then, a diverse set of biomarkers have been implicated as prognostic indicators in gliomas, including checkpoint molecules (PD-1, CTLA-4, TIM-3), growth/angiogenesis proteins (EGFR), and cytokines (TGF-β, IL-4, IL-13)." (PMID 35203944, 2022). "Altogether, their results indicated that Tau expression can induce changes in the glioma phenotype, through the regulation of the EGFR/TAZ/NF-κB pathway." (PMID 36358803, 2022).
glioma (continued). "In glioma, antibody-drug conjugate targeting EGFR combined with TMZ has shown positive results, although current targeted therapy alone has not significantly impacted survival." (PMID 35964070, 2022). "The [111In-DTPA, PEG3400-biotinyl]-EGF/SA-OX26 was injected intravenously in nude rats bearing an intracranial human U87 glioma, which over-expresses the EGFR." (PMID 35745855, 2022). "In the 2021 revised version, novel molecular indicators, including telomerase reverse transcriptase (TERT) promoter alterations and epidermal growth factor receptor (EGFR) gene amplification, are required to classify adult patients with gliomas." (PMID 36249824, 2022). "The EGFR pathway activity in glioma is regulated by another circRNA circular E-cadherin (circ-E-Cad) RNA, which encodes a secretory E-cadherin protein variant (C-E-Cad) synthesized through multiple-round open reading frame translation." (PMID 36009578, 2022). "CircE-Cad encodes for a peptide of 255 amino acid residues (C-E-Cad), which is secreted by glioma cells and stimulates the epidermal growth factor receptor (EGFR)." (PMID 35269953, 2022). "It is well known, that glioma cells overexpressed the epidermal growth factor receptor de2-7EGFR (or EGFRvIII)." (PMID 35956937, 2022). "The EGFR-driven signaling pathway induces not only the uptake and utilization of glucose but also the uptake and utilization of acetate in glioma cells." (PMID 35158782, 2022). "A high GPER1 level associated with a high expression of key genes involved in angiogenesis such as PDGFRB, which enhanced glioma cell migration and was proposed together with EGFR as a target for therapeutic agents." (PMID 36077653, 2022). "In contrast, epidermal growth factor receptor is regulated by downregulating miR-7 to decrease the proliferation and invasiveness of cultured glioma cells." (PMID 36199758, 2022). "EGFR induced radioresistance of glioma cells via triggering the PI3K–Akt and MEK–ERK pathways and attenuated cetuximab-mediated radiosensitization of squamous cell carcinoma cells via the JIP-4/JNK2 signaling pathway." (PMID 36119466, 2022). "Although the Chr 7 amplification was also observed in other subtypes of glioma, the highly expression of EGFR was infrequently determined in other subtypes." (PMID 36483593, 2022). "The epidermal growth factor receptor (EGFR) was highly altered in gliomas and the most amplified in GBM." (PMID 35912242, 2022). "In 2008, a study performed to understand the two mutually exclusive groups of gliomas carrying ‘1p19q codeletion’ and ‘EGFR amplification’, identified Atoh8 as one of the multiple differentially regulated genes." (PMID 35053134, 2022). "Using flow cytometry, it was observed that the uptake amount of EGFR ASODN delivered by G5 PAMAM-FA was two times that delivered by oligofectamine in C6 glioma cells." (PMID 36289715, 2022). "In glioma, genetic alterations, such as IDH mutation and EGFR amplification, are important contributors in shaping the tumour metabolic landscape." (PMID 35784470, 2022). "Han and Wang found that miR-3918 expressions were distinctly downregulated in glioma and its overexpression suppressed the proliferation and invasion of glioma cells via decreasing EGFR to modulate PI3K/AKT signal." (PMID 35497882, 2022). "We genotyped 13 EGFR exon SNPs in a case–control study that included 324 Korean patients diagnosed with glioma and 480 population-based controls." (PMID 36347915, 2022). "This is in perfect concordance with EPIC analysis that revealed the same seven gliomas being EGFR amplified." (PMID 35453544, 2022). "For instance, TILs are enriched in NF1 and RB1 mutated gliomas but depleted in EGFR-amplified and PTEN-deleted gliomas." (PMID 35203421, 2022).
glioma (continued). "We characterized two GBM-derived glioma stem cell (GSC) primary cell lines containing multiple EGFR-harbouring ecDNA (ecEGFR) populations (GCGR-E26 and GCGR-E28, referred to here as E26 and E28)." (PMID 36476408, 2022). "Detailed workup showed that EGFR amplification is a phenomenon of high-grade CNS WHO Grade 4 gliomas." (PMID 35453544, 2022). "The epidermal growth factor receptor (EGFRvIII) variation, which is prevalent in 30% of high-grade gliomas, is involved in oncogenesis and tumor development processes." (PMID 36120213, 2022). "Glioma cell lines U251, U251 EGFR, U251 ΔEGFR, U87, and U87 ΔEGFR were subjected to treatment with erlotinib alone (0–40 μM) and combined with luteolin (10 and 20 μM)." (PMID 36199696, 2022). "A further subgroup is EGFR amplificated glioma, where newer EGFR inhibitors showed improved BBB penetration with better clinical efficacy in salvage therapy." (PMID 35681794, 2022). "It is known that THZ1 inhibits the expression of receptor tyrosine kinases, such as EGFR, in high-grade glioma." (PMID 35406486, 2022). "Tripartite motif-containing protein 11 (TRIM11), overexpressed in glioma, promotes proliferation, invasion, migration, and glial tumor growth via the induction of EGFR." (PMID 35832194, 2022). "In the same time, miR-155, miR-410, and miR-181a/b correlated negatively with WNT5A, MET, and EGFR in plasma of high-grade glioma patients." (PMID 35646622, 2022). "EGFR directly influences a variety of aspects that mediate the glioma process and is a central mediator in glioma cell-TME interaction." (PMID 34687436, 2022). "Moreover, rs1050171 may affect EGFR gene expression and predispose patients to gliomas." (PMID 36347915, 2022). "Within IDH mutants, 1p/19q codeletion was associated with lower tumor acidity (p < 0.0001, sensitivity 76.9%, specificity 91.3%), while IDH wild-type, EGFR-amplified gliomas were more hypoxic (R2’ p = 0.024, sensitivity 66.7%, specificity 76.9%)." (PMID 35626127, 2022). "EGFR has been the target of treatment in glioma patients both in a highly selective pan-human EGFR inhibitor or immunotherapies." (PMID 35371978, 2022). "It seems that wild-type EGFR amplification is more important in regulating EMT in gliomas, but the high heterogeneity and angiogenesis mediated by EGFR vIII are also beneficial to EMT." (PMID 36338770, 2022). "Tuning T cell affinity through elevated scFv recognition of antigens can selectively target cells expressing EGFR at high density on glioma cells, while low-density EGFR cells impair functional affinity." (PMID 35326556, 2022). "Here, we analyzed 34 glioma specimens of WHO Grades I to IV with regard to EGFR amplification status using fluorescence in situ hybridization (FISH) and Illumina Infinium EPIC Bead Chip Arrays." (PMID 35453544, 2022). "For EGFR, which we considered the most potentially target, there were more significant results in Brain Lower Grade Glioma, both in the co-expression and survival." (PMID 33968733, 2021). "They demonstrated that expression of the EGFR in serum EVs can accurately differentiate high-grade and low-grade glioma patients, and EGFR in EVs were positively correlated with Ki-67 in the tumor tissue." (PMID 34671555, 2021). "EGFR is overexpressed in ~ 50–60% of gliomas, and its expression is positively correlated with malignancy grade." (PMID 33407703, 2021). "These were EGFR for all glioma (Cochran’s Q = 155.96, P = 1.72 × 10–28) and GBM (Cochran’s Q = 162.38, P = 3.49 × 10–27) subtype analyses." (PMID 33504897, 2021). "First-generation EGFR inhibitors such as erlotinib and gefitinib have been used in the clinical treatment of glioma patients, although less than 20% of patients presented a response to these treatments." (PMID 33762015, 2021). "Somatic mutations of gliomas with high B2M expression are associated with PTEN deletion and EGFR amplification." (PMID 33658560, 2021).
glioma (continued). "Functionally, NT5DC2 can act as a stabilizer of some oncoproteins by reducing ubiquitin‐mediated degradation, including fyn in glioma 3 and EGFR in HCC." (PMID 33993634, 2021). "Unexpectedly, C-E-Cad directly binds with the EGFR’s extracellular domain, thereby maintains glioma stem cell tumorigenicity." (PMID 34206026, 2021). "Limited efficacy has been achieved in the treatment of glioma through the application of epidermal growth factor receptor (EGFR) inhibitors, which is reported to be related to the poor permeability of the brain–blood barrier (BBB) to EGFR inhibitors." (PMID 34635007, 2021). "In this context, the synthesis of new PTs was performed efficiently and in vitro and in silico studies were conducted to assess the potential of compounds 1–13 as EGFR-targeted anti-glioma agents." (PMID 34681605, 2021). "Among glioma patients, those with glioblastoma multiforme tumors who have high EGFR expression levels and low levels of phosphorylated PKB/Akt had a better response to erlotinib treatment." (PMID 34976783, 2021). "On the other hand, mutations in EGFR leading to elevated PDGFR-beta expression in pericytes can increase infiltration of leukocytes, myeloid cells, and lymphocytes in gliomas." (PMID 34566988, 2021). "The EGFR gene, given its correlation to a poor prognosis, is an important analytical marker in gliomas." (PMID 33946969, 2021). "Other than gefitinib, the effects of clinical relevant EGFR inhibitors centered on glioma apoptosis are of interest." (PMID 33920356, 2021). "The role of Rab5 in glioma progression and resistance to anti-EGFR therapy is still a matter of debate." (PMID 34831480, 2021). "miR-7 appears to be an effective inhibitor of the EGFR signaling in glioma by direct inhibition of the EGFR and down-regulation of Akt signaling, leading to decreased invasiveness of glioma." (PMID 33790740, 2021). "This includes activation of TF by the oncogenic epidermal growth factor receptor (EGFR), with corresponding studies on glioma, epidermoid, colorectal, breast and endometrial carcinoma cells." (PMID 34205482, 2021). "Conversely, the disruption of the CD44/EGFR complex reduces ERK1/2 activation in U87MG glioma cells." (PMID 33744285, 2021). "Doses of gefitinib (~40 μM) inducing apoptotic cell death in glioma cells are way higher than those inhibiting EGFR signaling (~5 μM)." (PMID 33920356, 2021). "Analysis of gene expression of human glioma tissue samples deposited in the REMBRANDT database revealed a correlation between upregulation of RRAD in EGFR-expressing glioma patients and poorer prognosis." (PMID 33980886, 2021). "The glioma patient group with high EGFR expression showed poor prognosis compared to the glioma group with low EGFR expression." (PMID 34495991, 2021). "For example, it has been reported that the levels of NEAT1, a lncRNA, were regulated by EGFR pathway activity, and this was critical for glioma cell growth and invasion." (PMID 34206026, 2021). "Silencing of DYRK1A or TRAF2 increases EGFR degradation and inhibition of the growth of glioma cells." (PMID 34708541, 2021). "Our results highlight for the first time the instrumental role of LRP-1 in gefitinib-mediated EGFR internalisation and glioma cell dissemination." (PMID 34831480, 2021). "Meanwhile, the expression of CRNDE positively correlates with EGFR activation to modulate glioma cell growth." (PMID 34454479, 2021). "Blocking the gene expression of both EGFR and β-catenin significantly inhibited the glioma invasive ability." (PMID 33790740, 2021).